MCL1 (MCL1 apoptosis regulator, BCL2 family member)
Diseases named in the same sentence as MCL1 in open-access papers (continued):
Sharing a sentence is not in itself a finding about the gene and the disease.
multiple myeloma (continued). "Similarly, Mcl-1 has been identified as an essential survival protein in human myeloma cells as well as in lymphoid malignancies and in normal lymphoid cells." (PMID 17324269, 2007). "Importantly, dependency on MCL-1 in cancer cells may be exploited for therapeutic gain, and novel agents that specifically target MCL-1 are already undergoing clinical investigation as potential chemotherapeutics in acute myeloid leukemia (AML) and multiple myeloma (MM)." (PMID 35349392, 2022).
leukemia (210 papers, 2009 to 2026). A malignant (clonal) hematologic disorder, involving hematopoietic stem cells and characterized by the presence of primitive or atypical myeloid or lymphoid cells in the bone marrow and the blood. "Anti-apoptotic BCL2 family members, including BCL2, BCL-XL, and MCL1, suppress apoptosis and are upregulated in cancer cells, including leukemia cells, where their expression is associated with poor prognosis." (PMID 40796615, 2025). "In vitro experiments, our data showed that VAH enhanced the anti-leukemia effect via deeper inhibition of MCL1, BCL-XL, and increased activation of BCL2 Associated X, Apoptosis Regulator (BAX) in AML cell lines." (PMID 37120593, 2023). "NVP-2 displayed antiproliferative activity against numerous leukemia cell lines, associated with downregulation of MCL-1 and induction of apoptosis." (PMID 34041038, 2021). "FL/FLT3 pathway-directed STAT5 activation leads to increased expression of MCL-1, a hallmark biomarker of leukemia stem cells." (PMID 33691697, 2021). "We previously discovered in vivo synergistic anti-leukemia activity of venetoclax and S63845, as each drug causes marked compensatory upregulation of MCL1 and BCL2 protein levels when used as single agent in zebrafish." (PMID 34331013, 2021). "Previous studies showed that YM155 induces caspase-8 dependent apoptosis, in human leukemia cells, through downregulation of Survivin and Mcl-1 and, in glioma cell lines to promote loss of mitochondrial membrane potential and release of AIF to the cytosol." (PMID 31591437, 2019). "Benzyl isothiocyanate, an anti-cancer agent, causes G2/M cell cycle arrest and apoptosis in human leukemia cell lines via the down-regulation of Mcl-1." (PMID 26694491, 2015). "In this leukemia, both proteins are important mediators of cell survival, with Mcl-1 which is closely associated with adverse prognosis and chemoresistance." (PMID 26041884, 2015). "In contrast, an increase in the Bim/Mcl-1 association has been associated with enhanced apoptosis in leukemia cells co-exposed to BH3 mimetics and MEK1/2 inhibitors." (PMID 24594907, 2014). "In the present study we characterized a novel Mcl1 splice variant, which was cloned from human neuroblastoma and leukemia cells." (PMID 23872733, 2013). "Mcl-1 overexpression has been associated with progression in leukemia and some solid tumors including prostate cancer (PCa)." (PMID 20085644, 2010). "Of particular interest were the NOXA, Mcl-1 and Bim members of the Bcl-2 family since they have been implicated in the apoptotic regulation of various forms of leukaemia." (PMID 20156337, 2010). "Mcl-1 overexpression is associated with progression in leukemia and some solid tumors including prostate cancer (PCa)." (PMID 20085644, 2010). "More recently, lycorine causes a rapid turnover of protein levels of myeloid cell leukemia-1 (Mcl-1), which may play an important survival role in a variety of tumor cells including leukemia were reported." (PMID 23593220, 2013). "In addition, lycorine induced apoptosis in human leukemia cells via the mitochondria pathway and caused a rapid turnover of myeloid cell leukemia 1 (Mcl-1) protein, which occurred before caspase activation." (PMID 20682078, 2010). "Moreover, loss of MCL1 delayed the onset of BCR-ABL-transformed leukemia in a mouse xenograft model, with a strong selection against clones with the MCL-1 deletion, suggesting MCL-1 may be a better target for inhibition in Ph+ ALL." (PMID 36142863, 2022). "Impaired survival associated with low CDK9 expression, may be correlated with increased MCL1 expression since increased MCL1 expression has been demonstrated to be associated with CDK9 drug resistance in leukemia, although this has to be further evaluated in a larger cohort of patients." (PMID 32012890, 2020).
leukemia (continued). "Inhibiting CDK9 or CDK12/13 induced the rapid downregulation of the short-lived, anti-apoptotic Bcl-2 proteins Mcl1 and A1/Bfl1 in Jurkat leukemia cells and SUDHL1 lymphoma cells, whereas the expression of Bcl-2 and Bcl-xL remained unaffected." (PMID 42204137, 2026). "Several studies have demonstrated that B-cell lymphoma 2 (Bcl-2) Homology 3 (BH3)-mimetics induce MCL-1 up-regulation as a compensatory response in leukemia cells." (PMID 39924517, 2025). "HHT and gilteritinib can upregulate Ubiquitin Conjugating Enzyme E2 L6 (UBE2L6) together, promoting the degradation of Mcl-1 through the ubiquitin-proteasome pathway, and bring an effective drug target for FLT3-ITD mutated leukemia." (PMID 39949739, 2025). "Taken together, VEN-insensitive leukemia cells are characterized by increased MCL-1 expression and binding of pro-apoptotic BIM." (PMID 38961053, 2024). "JOSD1 was reported to stabilize MCL1 and inhibit mitochondrial-dependent apoptosis, which subsequently promoted chemotherapy resistance in leukemia." (PMID 39143074, 2024). "Research is ongoing to identify strategies to counteract primary and adaptive resistance mechanisms in leukemia, such as combining venetoclax with inhibitors of other anti-apoptotic proteins like MCL-1." (PMID 38675444, 2024). "Mcl-1 inhibitors appear interesting and target Mcl-1, which is frequently upregulated in leukemia, thereby contributing to resistance to chemotherapy." (PMID 39273651, 2024). "The Mcl-1 protein plays a more important role than the Bcl-2 protein in the development of leukaemia." (PMID 38658865, 2024). "Initially discovered in leukemia and lymphoma, antiapoptotic members of the Bcl-2 family, including Bcl-2, Bcl-xL, or Mcl-1, are frequently overexpressed in other neoplasia in order to block apoptosis in tumorigenesis." (PMID 38461295, 2024). "S63845, a specific MCL-1 inhibitor, has potent in vivo anti-tumor activity in several cancer models, including leukemia." (PMID 39684800, 2024). "It is noteworthy that VEN enhances T cell-mediated antileukemic activity by increasing ROS production and that MCL1 targeting can modulate leukemia cell metabolism, cell adhesion proteins, and leukemia–stromal interactions." (PMID 38539426, 2024). "Tumor cells regained sensitivity to ABT-737 or Venetoclax as Mcl-1 gene was knocked out in leukemia cells, which suggested Mcl-1 was the primary reason of resistance to anti-Bcl-2 compounds." (PMID 39372954, 2024). "Although MCL1-dependent leukemias are uncommon, inhibiting one or more of the key pro-survival proteins is critical for fighting AML." (PMID 38790277, 2024). "It was shown that leukemias are dependent on the continuous function of either MCL-1 or BCL-2 for survival." (PMID 37108344, 2023). "Accumulating evidence has indicated the critical pro-survival role of MCL-1 in hematological malignancies, making this protein an important target in leukemia therapy." (PMID 37108344, 2023). "Palytoxin-induced dephosphorylation of Bcl-2 further exacerbated the proapoptotic effect of Mcl-1 and Bcl-xL degradation in a range of leukemia cell lines." (PMID 37103372, 2023). "The response was associated with immune cell abundance and induced the proteomic profiles of leukemia cells to disrupt survival pathways and significantly reduced MCL1 and YTHDF2 to potentiate leukemic cell death." (PMID 37386016, 2023). "induced apoptosis in leukemia versus normal hematopoietic cells, through a process involving Mcl-1 down-regulation, which in turn potentiates BAX activation and mitochondrial translocation, culminating in apoptosis." (PMID 36926328, 2023). "Targeting FLT3 and Bcl-2 and/or Mcl-1 simultaneously resulted in a synergistic pro-apoptotic effect in FLT3mutant leukemia cells." (PMID 36865133, 2023). "Therapy-induced downregulation of MCL1 and suppression of p21 expressing leukemia cells emerged as shared features among patients." (PMID 37386016, 2023).
leukemia (continued). "The downregulation of Mcl-1 sensitizes AML to Bcl-2 inhibitor-induced leukemia cell killing, and we have also reported a highly synergistic effect of venetoclax with Mcl-1 inhibition recently." (PMID 36865133, 2023). "The effect of combining BCL-2 and MCL-1 inhibition by venetoclax and S63845 was evaluated in vivo and strongly enhanced anti-leukemia activity was found in a pre-clinical patient-derived xenograft model." (PMID 35031695, 2022). "High levels of MCL-1 expression are induced by FLT3 mutations in AML and are correlated with venetoclax resistance, leukemia relapse, and poor outcomes, suggesting a prominent role of MCL-1 as an anti-apoptotic protein in AML." (PMID 35409248, 2022). "Mcl-1 is an important antiapoptotic protein and plays a more important role than Bcl-2 in leukemia development and survival maintenance." (PMID 35443722, 2022). "For example, overexpression of BCL-2, an X-linked inhibitor of apoptosis protein (XIAP), and myeloid cell leukemia 1 (MCL-1) blocks the intrinsic apoptotic pathway and confers resistance to chemotherapy in leukemia." (PMID 35992795, 2022). "Directly targeting this reciprocity by combined BCL-2 and MCL-1 inhibition showed efficient anti-leukemia activity, providing strong evidence for further evaluation of this combinatorial approach." (PMID 35031695, 2022). "For example, the development and persistence of acute myeloid leukemia (AML), the most common adult leukemia, is significantly dependent on myeloid cell leukemia 1 (MCL‐1), a critical survival factor for cancer that can directly affect cell death pathways." (PMID 35648075, 2022). "The proportion of NK cells in the BM of AML patients effectively predicted their prognostic outcomes and a combination of NK cell-based immunotherapies with an MCL1 inhibitor showed synergistic anti-leukemia effects in vitro." (PMID 36276132, 2022). "MCL-1 has been recognized as the major critical protein accounting for the resistance of leukemia cells against FDA-approved BH3 mimetic drugs, such as ABT-737 that antagonizes BCL-2, BCL-xL, or BCL-w and venetoclax (ABT-199, the BCL-2 specific inhibitor)." (PMID 34294680, 2021). "For example, inhibition of EGF-R mediated Mcl1 induction improved Navitoclax effects in leukemia K562 cells, by destabilizing Mcl1 levels through the upregulation of NOXA expression." (PMID 34753495, 2021). "Elevated expression of MCL-1 has been observed in CML and AML patients and associated with poor clinical outcome and chemoresistance in leukemia cells." (PMID 34294680, 2021). "In acute myeloid leukemia (AML) and acute lymphoblastic leukemia (ALL), MCL1 is often elevated at relapse, suggesting a possible role for MCL1 in the survival of leukemia cells after chemotherapy." (PMID 32645016, 2020). "Mechanistically, CS055 promoted leukemia suppression through DNA double-strand break and altered unbalance of anti- and pro-apoptotic proteins (e.g., Mcl-1 and Bcl-xL downregulation, and Bim upregulation)." (PMID 32948748, 2020). "MCL-1 is highly expressed in leukemia and the expression of MCL-1 is correlated with chemotherapy response." (PMID 32907612, 2020). "Homoharringtonine (HHT) is a commonly used anti-leukemia drug with multiple mechanisms of action, including the downregulation of MCL1 expression." (PMID 33292251, 2020). "HMGB1 also increases the expression of monocyte chemoattractant protein 1 (MCP1) and myeloid cell leukemia 1 (Mcl1) to promote the migration of human leukemia monocytic THP1 cells, which is inhibited by glycyrrhizin (GL)." (PMID 32660524, 2020). "Inhibition of EGFR-MEK signaling pathway leads to the downregulation of Bcl-2 and induced myeloid leukemia cell differentiation protein Mcl-1 (Mcl-1) and promotes apoptosis to confer sensitivity to anti-EGFR treatments." (PMID 31527477, 2019). "S63845 was demonstrated to induce potent killing of MCL-1-dependent cancer cells, including leukemia and lymphoma cells, by activation of the BAX/BAK-dependent apoptotic pathway." (PMID 30972300, 2019).
leukemia (continued). "Consistent with above, previous reports have highlighted that increase in levels and addiction to MCL1 and/or Bcl-xL confers innate or acquired resistance to venetoclax in leukemia and lymphoma cells 29,30." (PMID 30647404, 2019). "Accordingly, by inhibiting Rac1, collagen/α2β1 integrin signaling inhibits drug-induced DNA damage and JNK activation, restores Mcl-1 levels thereby promoting leukemia chemoresistance." (PMID 31857649, 2019). "MCL-1 down-regulation by CDK inhibitor roscovitine or Mcl-1-shRNA dramatically increases ABT-737 lethality in human leukemia cells." (PMID 28659182, 2017). "This was surprising since multiple studies have suggested that Mcl-1 is necessary for mediating drug resistance in cancers including leukemias." (PMID 28520795, 2017). "The MCL1 downregulation in Ewing sarcoma cell lines agrees with previous data demonstrating MCL1 downregulation by mistletoe lectins in leukemia cells and by an oleanolic acid derivative in osteosarcoma cells." (PMID 27589063, 2016). "When UM-36 was applied to the panel of re-programmed leukemia cells it induced apoptosis in p185+ B-ALL cells re-programmed to express human MCL-1 (IC50 = 2.5 μM) and, to a lesser extent, in cells expressing BFL-1 (IC50 = 3.4 μM)." (PMID 26862853, 2016). "Our findings are consistent with a previous study that showed decreased expression of Mcl-1 in response to cyclin-dependent kinase inhibition which led to increased sensitivity of human leukemia cells to the BH3 mimetic ABT-737." (PMID 27353420, 2016). "In support of this, concomitant NOXA and MCL1 upregulation is observed in MYC-driven leukemias, and following activation of RAS in epithelial cells." (PMID 26910119, 2016). "This BIM SAHB (BIM 21-mer, residues 146-166) binds with high affinity to BCL-XL, BCL-W, MCL-1 and A1, and it induces mitochondrial apoptosis in leukemia/lymphoma cell lines and tumor regression in an animal model of human leukemia." (PMID 25970783, 2015). "Other relevant stapled peptides were described such as a SAHB modeled on the MCL-1 BH3 domain which was characterized as a selective MCL-1 inhibitor with proapoptotic properties in leukemia cell lines." (PMID 25970783, 2015). "In contrast, BEZ235 strongly suppressed expression of MCL-1 in a human leukemia cell line (BV173) and in ABT-199-resistant SU-DHL6 cells." (PMID 26460954, 2015). "Previous studies have shown that inhibition of the MTOR/4EBP1 pathway in leukemia cells leads to a reduction in the levels of the anti-apoptotic protein MCL1, with important implications for chemosensitivity." (PMID 26542945, 2015). "Studies performed by Koss B indicate that endogenous MCL-1 has anti-apoptotic activity that promotes survival during BCR-ABL transformation in established BCR-ABL(+) leukemia." (PMID 26036638, 2015). "Because of the critical pro-survival role of Mcl-1 in leukemia, we explored its role in ponatinib-induced apoptosis of CEL cells." (PMID 24472312, 2014). "Suggesting that Mcl-1 and Bcl-2 also regulated by miR-29a and miR-29b at post-transcriptional level and both of them contribute to the blocked apoptosis of leukemia cells in CML." (PMID 25006537, 2014). "CuE at 1–10 μM has also consistently decreased levels of the anti-apoptotic proteins XIAP, Survivin, and Mcl-1, and increased levels of the pro-apoptotic protein Bax in human leukemia HL-60 cells." (PMID 25072848, 2014). "This small molecule displaces Mcl-1 SAHB from its binding partner Mcl-1 and induces apoptosis through Bax/Bak activation in Mcl-1-dependent leukemia cells." (PMID 24525395, 2014). "Our results further support the report about the specificity of Maritoclax on Mcl-1 in leukemia cells." (PMID 24223823, 2013). "By serendipity we cloned a variant of the anti-apoptotic Bcl2-family member Myeloid cell leukemia-1 (Mcl1) from human neuroblastoma and leukemia cells." (PMID 23872733, 2013).